GAA (alpha glucosidase)
Diseases named in the same sentence as GAA in open-access papers (continued):
Sharing a sentence is not in itself a finding about the gene and the disease.
Pompe disease (continued). "Since Pompe disease arises from an insufficiency of the GAA enzyme, enzyme replacement therapy (ERT) is one therapeutic option." (PMID 32317649, 2020). "Enzyme replacement therapy (ERT) is the most common treatment for Pompe disease and involves the administration of recombinant human GAA (rhGAA)." (PMID 32214050, 2020). "Pompe disease (GSD II) is an autosomal recessive disorder caused by deficiency of the lysosomal enzyme acid-α-glucosidase (GAA, EC 3.2.1.20), leading to a generalized accumulation of lysosomal glycogen especially in the heart, skeletal and smooth muscle, and the nervous system." (PMID 33371305, 2020). "Pompe disease (PD, glycogen storage disease type II) (OMIM #232300) is an autosomal recessive condition caused by mutations in the acid-α-glucosidase (GAA) gene." (PMID 32796538, 2020). "Pompe disease (also termed glycogen storage disease type II; OMIM #232300) is caused by compound heterozygous or homozygous mutations of the GAA gene, which encodes the acid alpha-1,4-glucosidase (GAA)." (PMID 32290314, 2020). "Pompe disease (GSD II) is an autosomal recessive disorder caused by deficiency of the lysosomal enzyme acid-α-glucosidase (GAA, EC 3.2.1.20), leading to generalized accumulation of lysosomal glycogen especially in the heart, skeletal, and smooth muscle, and the nervous system." (PMID 33371305, 2020). "The one with infantile-onset Pompe disease was treated with recombinant alpha-glucosidase since the age of 8 days." (PMID 32014045, 2020). "Enzyme replacement therapy using recombinant human GAA [rhGAA] for Pompe disease has been facilitated by the development of the knockout mouse model which is deficient in the lysosomal α-glucosidase." (PMID 33260301, 2020). "Pompe Disease (Glycogen storage disease type II) is a severe, inherited neuromuscular disorder characterized by a deficit of the lysosomal acidα-glucosidase (GAA)." (PMID 31412596, 2019). "Pompe disease, or Glycogen Storage Disease type II a (GSD-IIa), is caused bydeficiency of lysosomal acid α-1-4-glucosidase (GAA)." (PMID 31132295, 2019). "Infantile onset Pompe disease (IOPD) is a rare and lethal genetic disorder caused by the deletion of the acid alpha-glucosidase (GAA) gene." (PMID 31867331, 2019). "Pompe disease (Glycogen Storage Disease type II, OMIM #232300), an autosomal recessive lysosomal storage disorder caused by deficiency of acid-α-glucosidase (GAA), results in lysosomal glycogen accumulation in all cell types, but mainly in muscle cells." (PMID 30902109, 2019). "Currently, the only approved ERT for Pompe disease is Chinese hamster ovary-derived recombinant GAA (alglucosidase alfa, Myozyme®/Lumizyme®, Genzyme, Cambridge, MA, USA)." (PMID 30943998, 2019). "Before the development of enzyme replacement therapy (ERT) with recombinant human GAA (rhGAA), treatment of Pompe disease was limited to palliative care." (PMID 30943998, 2019). "Pompe disease (glycogen storage disease type II, GSD II) is a progressive metabolic myopathy caused by a deficiency of lysosomal alpha-glucosidase." (PMID 30367637, 2018). "Screening for Pompe disease using a fluorometric assay using a 96-well plate reader for alpha-glucosidase began in 2005, initially in about half of the population, using the non-screened population as controls." (PMID 33072946, 2018). "Pompe disease, also known as type II glycogenosis, is a lysosomal storage disease (LSD) caused by mutation in the acid-α-glucosidase (GAA) gene." (PMID 28874182, 2017). "Recombinant human GAA (rhGAA) produced in CHO cells has been approved in 2006 for enzyme replacement therapy (ERT) to treat Pompe disease and has proven to be beneficial for patient’s survival and to stabilize the disease course." (PMID 29061980, 2017). "Here we present the high-resolution crystal structures of recombinant human GAA (rhGAA), the standard care of Pompe disease." (PMID 29061980, 2017).
Pompe disease (continued). "Pompe disease (glycogen storage disease type II, acid maltase deficiency, OMIM # 232300) is a lysosomal storage disorder caused by mutations in the acid α-glucosidase gene (GAA, EC 3.2.1.20)." (PMID 24715333, 2015). "In fact, a recent survey of Pompe disease-related mutant forms of GAA revealed a strong correlation between residual enzyme activity and trafficking to lysosomes as evident through proteolytic processing." (PMID 25036864, 2014). "While assessments of muscle function and strength have not been made in these mice and represent key areas of future experimentation, the hP545L GAA Tg/KO mice do represent an excellent biochemical model of Pompe disease." (PMID 25036864, 2014). "Pompe disease (glycogen storage disease type II; OMIM 232300) is an inherited neuromuscular disorder caused by a deficiency of acid alpha-glucosidase (GAA; OMIM 606800), the sole enzyme responsible for the breakdown of glycogen in the lysosomal compartment." (PMID 24383498, 2014). "The diagnosis of this patients group with late-onset Pompe disease depended on the combination of clinical manifestations, muscle biopsy, blood-based GAA activity assay and GAA gene analysis." (PMID 25526786, 2014). "Pompe disease (acid maltase deficiency, glycogen storage disease type II; OMIM 232300) is a lysosomal storage disorder caused by mutations in the gene (GAA) that encodes the lysosomal hydrolase acid α-glucosidase (GAA)." (PMID 25036864, 2014). "The ratio of Ph-a to Ph-b is relevant in Pompe disease because GAA, the other primary enzyme capable of degrading glycogen, is deficient." (PMID 23457523, 2013). "Pompe disease (OMIM 232300; acid maltase deficiency, glycogen storage disease type II) is an autosomal recessive deficiency of lysosomal acid alpha-glucosidase (GAA; OMIM 606800) that results in progressive glycogen accumulation." (PMID 23825616, 2013). "Pompe disease (OMIM 23200), also referred to as glycogen storage disease type II or acid maltase deficiency, is a lysosomal storage disease (LSD) caused by mutations in the gene (GAA) that encodes the lysosomal hydrolase acid α-glucosidase (GAA)." (PMID 22815812, 2012). "Recombinant human GAA (rhGAA) is the only approved enzyme replacement therapy (ERT) available for the treatment of Pompe disease." (PMID 22815812, 2012). "The clinical course of Pompe disease primarily depends on the residual acid alpha-glucosidase activity as determined by the genotype." (PMID 22676651, 2012). "ERT with recombinant GAA (rhGAA) is the primary treatment for Pompe disease." (PMID 40981304, 2025). "Pompe disease (OMIM 232300) is a rare metabolic myopathy, which is caused by a partial or total lack of the lysosomal enzyme acid alpha-glucosidase due to variants in GAA." (PMID 40471681, 2025). "Dried blood spot testing for Alpha-1,4 glucosidase (GAA) activity using tandem mass spectrometry confirmed the diagnosis of Pompe disease, showing significantly reduced enzymatic activity of 0.4 μmol/L/h (reference range for normal individuals: > 2.0 μmol/L/h)." (PMID 38500078, 2024). "Glycogen storage disease type II (MIM # 232300), also known as Pompe disease (PD), is a rare autosomal recessive metabolic disorder caused by the deficiency of the lysosomal acid α-1,4 glucosidase (GAA, EC 3.2.1.20)." (PMID 37106898, 2023). "Glycogen storage disease type II, also called Pompe disease (PD; OMIM#232300), is an autosomal recessive disorder resulting from malfunction of lysosomal acid α-glucosidase (GAA; EC 3.2.10.20) caused by mutations in the GAA gene (OMIM#606800)." (PMID 36517654, 2022). "Some NBS programs for Pompe disease, including ours, have shown that the combination of GAA enzyme assays using dried-blood spot (DBS) cards and GAA gene mutation analysis could be useful in distinguishing false-positive cases from patients with Pompe disease." (PMID 34922579, 2021).
Pompe disease (continued). "Pompe disease (glycogen storage disease type II, or acid maltase deficiency; OMIM 232300) is an autosomal-recessive disorder of metabolism caused by mutations in the lysosomal hydrolase, acid alpha-glucosidase gene (GAA)." (PMID 33953320, 2021). "From the RNA-Seq data set, we also generated a Pompe disease signature that consisted of the top 50% of altered genes with |log2FC| ≥ 2 and padj < 0.05, of which 243 were downregulated and 39 were upregulated in GAA−/− vs. WT mice." (PMID 33953320, 2021). "We also defined a muscle transcriptional signature of Pompe disease by comparing GAA−/− and wild-type mice, confirmed the presence of this signature in IO Pompe myobundles, and detected a partial reversal of the signature upon in vitro treatment of myobundles with rhGAA." (PMID 33953320, 2021). "One likely explanation for this is that rhGAA maturation was inefficient or incomplete in our cell lysates of patients with Pompe disease, in contrast to previously published results obtained using purified mature GAA from WT production cell lines or human placenta." (PMID 33971197, 2021). "Pompe disease (Glycogen storage disease type II, OMIM 232300) is an autosomal inherited recessive disorder caused by the partial or complete deficiency of the lysosomal enzyme acid α-glucosidase (GAA)." (PMID 33168984, 2021). "All Pompe disease NSCs showed no GAA activity, suggesting the GAA deficiency nature was preserved in the Pompe disease NSCs." (PMID 33375166, 2020). "Glycogen storage disease (Pompe disease) is an autosomal recessive lysosomal storage disease caused by a deficiency of acid α-1,4-glucosidase encoded by the GAA gene (GAA [MIM: 606800] acid maltase, EC 3.2.1.20/3, 17q25.3), which is a key enzyme in hydrolyzation of lysosomal glycogen to glucose." (PMID 32126021, 2020). "Pompe disease, also known as acid maltase deficiency and glycogen storage disease type II (MIM# 232300), is a rare, progressive, autosomal recessive inheritance (HP:0000007) disorder caused by deficient acid α‐glucosidase (GAA), the lysosomal enzyme that breaks down glycogen." (PMID 31342611, 2019). "Pompe disease (OMIM 232300, glycogen storage disease type II or acid maltase deficiency) is one of the lysosomal storage disorders, caused by an inborn defect of lysosomal acid α-glucosidase (GAA)." (PMID 29044175, 2017). "We verified prior to the in vivo experiments that the recombinant GAA coded by our plasmid was correctly processed, secreted and endocytosed in vitro by using infantile Pompe disease fibroblasts grown in the presence of medium from CAG-hgaa transfected HEK293 cells." (PMID 28874182, 2017). "Pompe disease (glycogen storage disease type II, acid maltase deficiency, OMIM #232300) is an autosomal recessive lysosomal glycogen storage disorder caused by a deficiency of the lysosomal enzyme acid α-glucosidase (GAA)." (PMID 25526786, 2014). "Enzyme replacement therapy (ERT) currently is the only approved treatment for Pompe disease, administered as a bi-weekly intravenous infusion of recombinant human GAA (rhGAA; alglucosidase alfa, marketed as Myozyme and Lumizyme, Genzyme Corp., a Sanofi company, Cambridge, MA)." (PMID 25036864, 2014). "Glycogen storage disease type II (Pompe's disease) is an autosomal recessive lysosomal storage disease caused by a deficiency of acid α-1,4-glucosidase (GAA; acid maltase, EC; 3.2.1.20/3), which is a key enzyme in hydrolyzation of lysosomal glycogen to glucose." (PMID 25093132, 2014). "Pompe disease (PD), also referred to as acid maltase deficiency (AMD) or glycogen storage disease type II (GSDII), is an autosomal recessive disorder caused by a deficiency of the lysosomal enzyme acid-α-glucosidase (GAA)." (PMID 24772354, 2014). "Glycogenosis type II, a rare autosomal recessive lysosomal storage disorder (LSD), is caused by mutations in the acid α-glucosidase (GAA) gene encoding for the lysosomal hydrolase GAA that is involved in the breakdown of glycogen into glucose." (PMID 23391190, 2013).
Pompe disease (continued). "Pompe disease – or glycogenosis type II – (PD, MIM 232300) is an autosomal recessive lysosomal storage disorder (LSD), caused by the deficient activity of the acid alpha glucosidase (GAA) enzyme due to pathogenic variants in the GAA gene (MIM 606800; NM_000152.5)." (PMID 39905333, 2025). "Pompe disease (OMIM 232300), also known as Glycogen Storage Disease Type II, is an autosomal recessive disorder caused by deficiency of the lysosomal enzyme acid alpha-1,4-glucosidase (GAA), leading to toxic accumulation of glycogen in cardiac, skeletal, and smooth muscle." (PMID 36246652, 2022). "Pompe disease (glycogen storage disease type II or acid maltase deficiency, OMIM #232300) is a rare inherited metabolic and neuromuscular disorder, caused by disease-associated variants in the GAA gene, leading to deficiency of the lysosomal enzyme acid α-glucosidase." (PMID 35109913, 2022). "Pompe disease (OMIM No. 232300, glycogen storage disease type II), an autosomal recessive, multisystemic neuromuscular disorder, is caused by biallelic mutations in the GAA gene encoding for the lysosomal enzyme acid alpha-glucosidase (GAA enzyme, EC 3.2.1.20) that degrades lysosomal glycogen." (PMID 35813979, 2022). "However, plasma free/total acyl-carnitine profile was normal and analysis of exons 2-20 of the glucosidase alpha acid (GAA) gene from her blood revealed no mutation known to be associated with Glycogen Storage Disease II/Pompe disease." (PMID 35071363, 2021). "Pompe disease (Glycogen storage disease type II, GSD II, acid alpha-glucosidase deficiency, acid maltase deficiency, OMIM # 232300) is an autosomal-recessive lysosomal storage disorder caused by a deficiency of acid alpha-glucosidase (GAA, acid maltase, EC 3.2.1.20, Swiss-Prot P10253)." (PMID 22676651, 2012). "Pompe disease (Glycogen storage disease type II, GSD II, acid alpha-glucosidase deficiency, acid maltase deficiency, OMIM # 232300) is an autosomal-recessive lysosomal storage disorder due to a deficiency of acid alpha-glucosidase (GAA, acid maltase, EC 3.2.1.20, Swiss-Prot P10253)." (PMID 22676651, 2012). "In patients with late-onset Pompe disease (LOPD), the efficacy of the enzyme replacement therapy (ERT) with recombinant human alpha-glucosidase (rhGAA) is difficult to evaluate, due to the clinical heterogeneity and the small sample sizes in published studies." (PMID 33851281, 2022). "Enzyme replacement therapy (ERT) with recombinant human GAA (rhGAA), derived from Chinese hamster ovary (CHO) cells, was approved as registered treatment for patients with Pompe disease in 2006 (Myozyme, Genzyme Corporation)." (PMID 36284764, 2022). "The current standard of care treatment for Pompe disease, enzyme replace therapy (ERT), consisting of frequent intravenous infusions of recombinant human GAA (rhGAA), reduces muscle glycogen and can improve muscle function and patient quality of life." (PMID 33953320, 2021). "Of the 17 known GSDs, Pompe disease (GSD II) and Danon disease (also classifiable as an integral membrane protein disorder) are categorized as LSDs given their involvement of the lysosomal acid α-glucosidase (GAA) and LAMP2, respectively." (PMID 32435656, 2020). "This Pompe disease NSC model was used to evaluate therapeutic responses to δ-tocopherol, hydroxypropyl-beta-cyclodextrin (HPβCD), and recombinant human GAA (rhGAA)." (PMID 33375166, 2020). "Enzyme replacement therapy (ERT) with recombinant human GAA (rhGAA) has been approved by the United States Food and Drug Administration (FDA) for Pompe disease." (PMID 33375166, 2020). "No GAA enzyme was detected by western blotting in the Pompe disease NSCs; the same was also observed in the patient-derived fibroblasts, the source cells from Coriell Cell Repository." (PMID 33375166, 2020).
Pompe disease (continued). "Glycogenosis type II (GSDII or Pompe disease) is an autosomal recessive disease, often characterized by a progressive accumulation of glycogen within lysosomes caused by a deficiency of α-1,4-glucosidase (GAA; acid maltase), a key enzyme of the glycogen degradation pathway." (PMID 24107549, 2013). "In a cross-sectional single-centre study we clinically assessed 3 patients with classic infantile Pompe disease and 39 patients with non-classic presentations, measured their acid alpha-glucosidase activities and analysed their GAA genes." (PMID 22676651, 2012). "Depending on the residual GAA enzyme activity, the disease either develops during the first months of life as the classic infantile Pompe disease (IOPD), or later in life (childhood, adolescence or adulthood) with a milder phenotype known as late-onset Pompe disease (LOPD)." (PMID 36009380, 2022). "These nonspecific symptoms often make Pompe disease clinically difficult to differentiate from other neuromuscular diseases, but valuable evidence can be provided by measurement of decreased GAA activity, observations of vacuoles in muscle fibers on muscle biopsy, and genetic tests of the GAA gene." (PMID 25526786, 2014). "Glycogenosis type II (GSDII, or Pompe disease; MIM 232300) is an autosomal recessive storage disorder due to mutations of the acid α-glucosidase gene (GAA) on the chromosome 17q21-23 which causes absent or deficient activity of the lysosomal enzyme acid α-glucosidase (GAA)." (PMID 24107549, 2013).